FOXO1 (forkhead box O1)
Diseases named in the same sentence as FOXO1 in open-access papers (continued):
Sharing a sentence is not in itself a finding about the gene and the disease.
diabetic cardiomyopathy (continued). "Ang IV treatment dose-dependently attenuated left ventricular dysfunction and remodeling in a mouse model of diabetic cardiomyopathy, and the mechanism involved stimulation of AT4R, suppression of FoxO1 nuclear translocation, and inhibition of FoxO1-mediated overactive autophagy." (PMID 34522203, 2021). "Resveratrol, carnosic acid, beta carotene, and curcumin can activate autophagy through the SIRT1/FOXO1/Rab7 axis, PI3K/Akt/mTOR, activate AMPK and JNK1, phosphorylated Bcl-2 and Bim and subsequently disrupted their interactions with Beclin1 to treat diabetic cardiomyopathy." (PMID 37810881, 2023). "Finally, FoxO1 inhibition and large-dose Ang IV had no synergistic effect on diabetic cardiomyopathy, but FoxO1 inhibition completely reversed the detrimental effects of divalinal administration." (PMID 34522203, 2021). "Thus, we hypothesized that Ang IV protects against diabetic cardiomyopathy via stimulation of AT4R and inhibition of FoxO1-enhanced autophagy, and a series of in vivo and in vitro experiments were designed and performed in this study to test this hypothesis." (PMID 34522203, 2021).
non-small cell lung carcinoma (31 papers, 2014 to 2025). A group of at least three distinct histological types of lung cancer, including non-small cell squamous cell carcinoma, adenocarcinoma, and large cell carcinoma. "The expression level of Foxo1 was decreased, while that of lncRNA colon cancer associated transcript 1 (CCAT1) was elevated in non-small-cell lung cancer (NSCLC) cells." (PMID 35656022, 2022). "Intriguingly, miR-183 enhances the survival of non-small cell lung cancer cells by targeting forkhead box O1 (FOXO1)." (PMID 32364530, 2020). "This study investigated the role of miR-3188 on the proliferation of non-small cell lung cancer cells and its relationship to FOXO1-modulated feedback loop." (PMID 30618730, 2018). "Furthermore, another study reported that ESM-1 expression was regulated via the JAK/STAT3 pathway in EGFR-activated non-small-cell lung cancer cells and induced by FoxO1 nuclear localization in cultured endothelial cells under hypoxic conditions." (PMID 36077661, 2022). "TCF19 gene can promote the proliferation of non-small cell lung cancer cells by inhibiting FOXO1." (PMID 36712848, 2022). "In contrast, KDM6B overexpression induced cell apoptosis in non-small cell lung cancer (NSCLC) via translocation of FOXO1 indicating that the role of KDM6B may be cell type dependent." (PMID 34220955, 2021). "ESR1/2 might directly or indirectly regulate oncogenic pathways in non-small-cell lung cancer, and FOXO1 expression is a favourable prognostic factor in non-small-cell lung cancer." (PMID 32457348, 2020). "Similarly, the knockdown of KDM6B inhibits cell apoptosis and promotes cell growth by reducing the nuclear translocation of FOXO1 in non-small cell lung cancer cells." (PMID 28947976, 2017). "However, the roles and regulatory mechanisms of CGN and FOXO1 are unknown in non-small cell lung cancer (NSCLC) and normal human lung epithelial (HLE) cells." (PMID 38338691, 2024). "Similarly, Sunet al. reported that the sensitivity of non-small-cell lung cancer cells to DDP could be promoted by FOXO1 and FOXO3a." (PMID 35983979, 2022). "Studies in non-small cell lung cancer (NSCLC) have shown that WT1-interacting protein inhibits cell proliferation and tumorigenicity through the AKT/FoxO1 axis." (PMID 34692659, 2021). "In the case of non-small cell lung cancer (NSCLC), FoxO1 phosphorylation facilitates cell proliferation and prevents apoptotic cell death, indicating that the nuclear barring of FoxO1 inhibits signaling pathways of programmed cell death." (PMID 33804729, 2021). "In non-small cell lung cancer patients, KDM6B significantly decreases in the serum and may play a pro-apoptotic role via promoting the nuclear translocation of FOXO1." (PMID 35783266, 2022).
diabetic nephropathy (30 papers, 2013 to 2026). "Another study has confirmed that TIMP-3 deficiency contributes to the development of diabetic nephropathy through FoxO1/STAT1 interactions." (PMID 38774282, 2024). "Dysregulation of FOXO1 is associated with diabetic kidney disease, encouraging investigational research of FOXO1 as a therapeutic target." (PMID 37814337, 2023). "Alternative targets for miR-216a-5p include the transcription factor FoxO1, which is related to the human mesangial cell proliferation in diabetic nephropathy, and BAX, which is associated with the protection neurons from apoptosis in Parkinson’s disease." (PMID 33415108, 2020). "The loss of TIMP3 can lead to diabetic kidney disease in both human and mouse via the interplay of FOXO1 and STAT1." (PMID 29796115, 2018). "The transcription factor Foxo1 has been implicated in progression of nephropathies of different etiology, including hypertensive and diabetic nephropathy." (PMID 27736906, 2016). "Interestingly, antisense-to-RNA-2 (CTBP1-AS2) can ease the oxidative stress, ECM accumulation, and inflammation caused by high levels of HG in diabetic nephropathy by regulating the miR-155-5p/FoxO1 axis." (PMID 38671903, 2024). "Thus, the authors suggested that the improvement in diabetic nephropathy mediated by RVT may be related to increased expression of FoXO1, if oxidative stress is implicated in the pathogenesis of diabetic nephropathy." (PMID 29104258, 2017). "Collectively, these findings provide a robust mechanistic rationale for investigating the FABP4/FOXO1 pathway in relation to macrophage dynamics and senescence in diabetic kidney disease, supporting the relevance of our experimental model." (PMID 41471323, 2025). "In diabetic nephropathy patients, lncRNA 01619 is downregulated, de‐repressing miR‐27a‐mediated suppression of Forkhead box protein O1 (FOXO1)." (PMID 39072992, 2024). "In a previous study, CTBP1-AS2 alleviates oxidative stress and inflammation induced by high-glucosethrough miR-155-5p/FOXO1 axis in diabetic nephropathy." (PMID 37790209, 2023). "Atrasentan, an antagonist of endothelin 1 receptor subtype A (ETA), was able to ameliorate diabetic kidney disease, by downregulating miR-21 expression, enhancing Foxo1 expression and upregulating autophagy." (PMID 35237600, 2022). "Metformin enhances autophagy via the AMPK/SIRT1-FOXO1 pathway in diabetic kidney disease, which suggests the involvement of FOXO1 in autophagy." (PMID 35126526, 2022). "This study aimed to explore the effects and mechanism of FoxO1 on ROS production in diabetic nephropathy." (PMID 33473269, 2021). "FOXO1 can reduce tubulointerstitial fibrosis and tubular apoptosis in diabetic nephropathy by targeting STAT1 signaling." (PMID 34867446, 2021). "The present study provides some ideas for FoxO1/SERPINB1 that can relieve the symptoms of ROS production in diabetic nephropathy." (PMID 33473269, 2021). "Taken together, the results showed that FoxO1/SERPINB1 ameliorates ROS production—induced oxidative stress in diabetic nephropathy vivo or vitro model." (PMID 33473269, 2021). "The detailed mechanism by which FoxO1/SERPINB1 ameliorates ROS production in diabetic nephropathy needs further investigation." (PMID 33473269, 2021). "We identify similar changes in expression of human TIMP3 and FoxO1 in renal biopsies from patients with diabetic nephropathy." (PMID 23401241, 2013). "This study reported that FoxO1 regulated SERPINB1 to reduce ROS production in diabetic nephropathy." (PMID 33473269, 2021). "This study found that FoxO1 reduced oxidative stress in diabetic nephropathy vivo or vitro model." (PMID 33473269, 2021). "Nevertheless, there were only a very limited number of studies that have characterized SIRT1 genes for DN in Japanese Caucasians, while no study focused on the association between FOXO1 gene and diabetic nephropathy." (PMID 28860538, 2017). "SIRT1 and FOXO1 play an important role in the pathogenesis of diabetic nephropathy (DN)." (PMID 28860538, 2017).
diabetic nephropathy (continued). "To investigate the molecular role of FoxO1 in the regulation of autophagy in diabetic nephropathy, we generated Timp3knockdown cells by stably transfecting SV40 MES13 cells with three shRNA plasmids that target different sequences in the Timp3 mRNA (T3kd MES13)." (PMID 23401241, 2013). "Although, the mechanism by which the SIRT1 polymorphism contributes to conferring susceptibility to diabetic nephropathy remains to be elucidated, combining the present finding with a previous report, SIRT1 and FOXO1 may be considered a good new candidate gene for diabetic nephropathy." (PMID 28860538, 2017). "Therefore, our results suggest that the SNPs within SIRT1 and FOXO1 might be involved in the process of diabetic nephropathy in Henan Han Chinese population." (PMID 28860538, 2017). "In diabetic kidney disease, STAT1 activation was observed, and the expression of the Forkhead box O1 (FoxO1) was decreased." (PMID 41074478, 2025). "In diabetic kidney disease, metformin relieved oxidative stress and enhanced autophagy via the AMPK/SIRT1 Foxo1 pathway." (PMID 36081940, 2022). "Studies on kidney biopsies from patients with diabetic nephropathy confirmed a significant reduction in TIMP3, FoxO1 and FoxO1 target genes involved in autophagy compared to controls, while STAT1 expression was strongly increased." (PMID 23401241, 2013). "By restoring the nuclear localization and transcriptional activity of FOXO1/3a, SIRT1 may facilitate the expression of target genes that protect against high glucose-induced mesangial cell injury in diabetic nephropathy." (PMID 39014438, 2024).
Hyperinsulinemia (29 papers, 2011 to 2025). An increased concentration of insulin in the blood. "On the contrary, other studies have shown that transgenic mice overexpressing constitutively active FOXO1 (CA-FoxO1) in liver exhibit decreased fasting TG and cholesterol despite of hyperinsulinemia and suppressed hepatic DNL and Srebp1-c expression." (PMID 39264516, 2024). "Mechanistically, compensatory hyperinsulinemia increases pancreatic PI3K/AKT signaling, which decreases FoxO1 activity and causes an increase in PDX1 activity and β-cell mass." (PMID 37941908, 2023). "Our results demonstrated that the intrauterine hyperinsulinemia environment has increased hepatic FoxO1 levels and subsequently increased expression of DNMT3A and epigenetic alterations on IGF2/H19 DMRs." (PMID 35432202, 2022). "In conclusion, our study demonstrated that intrauterine hyperinsulinemia increased hepatic FoxO1 levels and contributed to the upregulation of DNMT3A, subsequently inducing the downregulation of IGF2/H19 expression in the liver of GDM-F1 mice." (PMID 35432202, 2022). "This is corroborated by the fact that the translocation of GLUT4 to the cell surface is blunted, while the nuclear exclusion of FoxO1 is maintained in adipocytes with compromised insulin signaling (hyperinsulinemia)." (PMID 32244542, 2020). "The permanent nuclear exclusion of FoxO1 during hyperinsulinemia leads to the progression of adipocytes differentiation, repressing the lipolytic pathway and enhancing triglyceride accumulation." (PMID 32244542, 2020). "To further examine the effect of HB on hyperinsulinemia, we studied the interaction of FoxO1, PGC-1α, and NF-κB in HEK293T cells using insulin-treated cells." (PMID 30811347, 2019). "Although study has shown that rats with hyperinsulinemia have the specific FOXO1 protein, which can increase the formation of cholesterol into bile." (PMID 25070766, 2014). "Based on the ChIP-seq data, the same FOXO1 feedback loop influencing Igf1r, Insr, Irs1, and Irs2 may be present in other tissues experiencing hyperinsulinemia conditions." (PMID 40105689, 2025). "Given the fact that offspring of obese dams exhibit hyperinsulinemia at P2142, insulin and IL-6 signaling might converge on FoxO1." (PMID 35896539, 2022). "During IR and hyperinsulinemia, the autophagy activity and transcription levels of genes such as Atg7 are inhibited; this is closely related to transcriptional regulation mediated by the downstream signaling molecule FoxO1." (PMID 36147338, 2022). "This selective impairment in FoxO1 phosphorylation leads to increased expression of gluconeogenic enzymes, glucose intolerance, hyperinsulinemia, further activation of hepatic aPKC and Akt, and further increases in expression of lipogenic enzymes and proinflammatory factors." (PMID 26237474, 2014). "Hence, the preprandial hyperinsulinemia could lead to activation of insulin signaling, abrogating FOXO1 activity." (PMID 30532187, 2018). "Under chronic hyperinsulinemia, the PI3K–Akt–FoxO1 pathway responsible for suppressing hepatic glucose production (HGP) becomes desensitized first, whereas the SREBP-1c branch that promotes DNL remains relatively intact." (PMID 40950956, 2025). "Hyperinsulinemia induced IGF1 resistance, accompanied by reduced IGF1R protein, as well as Igf1r and Irs2 mRNA expression via over-activation of phosphoinositide 3-kinase/forkhead box O1 (PI3K-FOXO1) signaling." (PMID 40105689, 2025). "Finally, metabolic stress in the form of hyperinsulinemia promoted cellular IGF1 resistance via downregulation of Igf1r mRNA and protein, through a phosphoinositide 3-kinase/forkhead box O1 (PI3K-FOXO1)-mediated transcriptional mechanism." (PMID 40105689, 2025). "EPA, but not the other n3-PUFAs, reduced hepatic FoxO1 which suggests greater inhibition of gluconeogenesis; however, this potential mechanism did not explain the improvements in fasting hyperinsulinemia, or the HOMA-IR score observed in the faEPA group." (PMID 31022865, 2019).
Hyperinsulinemia (continued). "In addition to lower levels of FAS, the EPA diet resulted in a novel reduction of FoxO1, although this did not alter the hyperinsulinemia." (PMID 31022865, 2019).
liver fibrosis (29 papers, 2014 to 2026). "Following MASH diets, Lyz-IFNγR2−/− mice are rescued from developing liver fibrosis, which is associated with increased hepatic expression of forkhead box protein O1 (FoxO1) and reduced fibroblast growth factor (FGF) 21 levels." (PMID 38951527, 2024). "First, we preliminarily analyzed the association between miR-183-5p and FOXO1 by detecting FOXO1 expression in cholestatic liver fibrosis and normal fibrosis." (PMID 34867446, 2021). "Aligning with these findings, we observed that metabolic stress upregulated Foxo1 expression in three different mouse models of liver fibrosis." (PMID 41424862, 2026). "FoxO1 was upregulated in a CCl4-induced mouse model of hepatic fibrosis, and knockdown of FoxO1 resulted in significantly reduced TGF-β1 secretion by hepatocytes, which impeded HSCs activation induced by paracrine TGF-β1." (PMID 40761743, 2025). "The Akt/FoxO1 signaling pathway critically influences liver fibrosis by modulating cell survival and proliferation." (PMID 40076811, 2025). "In contrast to Foxo1M-KO, Foxo1/Notch1M-DKO augmented liver fibrosis, with concomitant increases in the mRNA expression of profibrotic genes, including αSMA, Col1α1, TGF-β1, CCL2, and TIMP1, in the liver after HFD feeding." (PMID 39122845, 2024). "For example, adenoviral overexpression of FoxO1 in wild-type mice promoted liver fibrosis and hepatic stellate cell activation induced by CCL4 injection, whereas this effect was blocked in mice lacking liver-specific TGF-β1." (PMID 39382800, 2024). "Specific knockout of FOXO1 can significantly increase the expression of inflammatory and fibrotic genes in the liver, thereby accelerating liver fibrosis." (PMID 39021599, 2024). "In hepatic fibrosis, FOXO1 inhibits the activation, transdifferentiation, and proliferation of hepatic stellate cells." (PMID 36578501, 2022). "BBR decreased the phosphorylation of FoxO1(forkhead) box O1 and Akt in rat liver fibrosis produced by bile duct ligation, as well as in HSC." (PMID 35744831, 2022). "In contrast, lipid peroxidation caused by upregulation of TGF-β-mediated expression and dysfunction of antioxidant enzymes is inhibited by esculetin therapy, thus reducing liver fibrosis by acting on the PI3K/FoxO1 pathway." (PMID 36293500, 2022). "In summary, our study shows that miR-183-5p is upregulated, whereas FOXO1 is poorly expressed, in activated HSCs and cholestatic liver fibrosis models." (PMID 34867446, 2021). "To further clarify the specific mechanism of miR-183-5p and FOXO1 in liver fibrosis, we used a lentivirus to overexpress FOXO1 in activated LX-2 cells, which transfected with the control agomir and miR-183-5p agomir." (PMID 34867446, 2021). "The published data have suggested a potential role of FoxO1 in hepatic fibrosis, as a constitutive activation of FoxO1 in vitro accompanied by the enhanced expression of p27kip1 has been demonstrated." (PMID 24741631, 2014). "Therapeutically targeting this pathway with inhibitors that block FoxO1 phosphorylation or restore its function may effectively reduce liver fibrosis by diminishing HSC activation, enhancing apoptosis, and alleviating inflammation." (PMID 40076811, 2025). "Furthermore, increased hepatic Tgfb1 gene expression observed in livers of CCl4‐injected Foxo1S273D mice further confirms the role of Foxo1 in regulating TGF‐β1 in liver fibrosis." (PMID 40479577, 2025).